RN7SL535P (RNA, 7SL, cytoplasmic 535, pseudogene)
Gene: Miscellaneous RNA gene on chromosome 7 (143,290,615 to 143,290,910, forward strand). Ensembl gene ENSG00000239419.
Homologues: Orthologues: chimpanzee Metazoa_SRP (99% identical), macaque Metazoa_SRP (93% identical). Paralogues in human: RN7SL1 (82% identical), RN7SL2 (81% identical), RN7SL3 (81% identical), RN7SL743P (81% identical), RN7SL113P (80% identical), RN7SL664P (80% identical), RN7SL126P (80% identical), RN7SL786P (80% identical), RN7SL220P (79% identical), RN7SL408P (79% identical), RN7SL47P (79% identical), RN7SL88P (79% identical), and 702 more.